VAV3 (vav guanine nucleotide exchange factor 3)
Diseases named in the same sentence as VAV3 in open-access papers (continued):
Sharing a sentence is not in itself a finding about the gene and the disease.
Skin Tumor (3 papers, 2013 to 2021). "Using genetically engineered mice, we show here that Vav2 and Vav3 favor cooperatively the initiation and promotion phases of skin tumors." (PMID 23935450, 2013). "Using this strategy, we have unveiled a Vav2/Vav3-dependent and cancer-specific autocrine/paracrine program that contributes to the initiation and promotion phases of skin tumors." (PMID 23935450, 2013). "Given the critical roles that extracellular factors play in both the initiation and promotion phase of skin tumors, we investigated whether they could be involved in the tumorigenic defects observed in Vav2−/−;Vav3−/− keratinocytes." (PMID 23935450, 2013). "Adding further evidence to the connection between Vav2 and VAV3 in cancer, genetic analysis has shown that VAV2 and VAV3 depletion decreases carcinogen-induced skin tumor formation while maintaining skin homeostasis in mice." (PMID 34571765, 2021).
colon adenocarcinoma (2 papers, 2014 to 2024). "For colon adenocarcinoma, the somatic mutations in four genes were significantly enriched in protein pocket regions: B2M (P = 3.1 × 10-4), IFNA2 (P = 3.1 × 10-4), VAV3 (P = 6.6 × 10-4), and ETV6 (P = 1.0 × 10-3)." (PMID 25360158, 2014). "However, despite its oncogenic effects and upregulation in several tumors, VAV3 expression is downregulated in certain cancers, including colon adenocarcinoma, head and neck squamous cell carcinoma, kidney cancer, lung adenocarcinoma, and prostate adenocarcinoma, as indicated by TCGA datasets." (PMID 39200159, 2024).
colon cancer (2 papers, 2014 to 2019). "To demonstrate the potential value of our approach, we identified four putative cancer genes (RWDD1, NCF1, PLEK, and VAV3), whose expression was associated with poor survival rates in melanoma, lung, or colon cancer patients." (PMID 25360158, 2014). "Building from our approach, we identified four new putative cancer genes (RWDD1, NCF1, PLEK, and VAV3), whose expression profiles were found to be associated with poor survival rates in melanoma, lung, or colon cancer patients." (PMID 25360158, 2014). "Interestingly, colon cancer patients with downregulated VAV3 expression were observed to possess significantly poorer survival rates (P = 0.02)." (PMID 25360158, 2014). "VAV3, ACSL6, GNG4, and KRT23 were significantly enriched in gene set defined as “downregulated genes discriminating between MSI and MSS colon cancers”." (PMID 31008109, 2019).
Crohn disease (2 papers, 2013 to 2022). A gastrointestinal disorder characterized by chronic inflammation involving all layers of the intestinal wall, noncaseating granulomas affecting the intestinal wall and regional lymph nodes, and transmural fibrosis. "Importantly, 4 of these candidate genes are key in pathways relevant in the context of human Crohn’s disease (FcgR1, Vav3, Vcam1 and Ctss), a disease with highly similar pathology to both the IL10 deficient and T. muris models of colonic inflammation." (PMID 23442222, 2013).
escherichia coli infection (2 papers, 2013 to 2015). Infection with the organism Escherichia Coli. "PRKC (including PRKCA and PRKCB), along with VAV (VAV2 and VAV3) genes also feature in various high ranking immunological pathways including T cell signaling, Pathogenic Escherichia Coli Infection and Natural Killer Cell Mediated Cytotoxicity." (PMID 24278029, 2013).
metabolic syndrome (2 papers, 2021). A cluster of metabolic risk factors for CARDIOVASCULAR DISEASES and TYPE 2 DIABETES MELLITUS. "Vav3-deficient mice on chow diet developed metabolic syndrome, non-alcoholic fatty liver disease (NAFLD) and type 2 diabetes, but not increased adiposity." (PMID 33923452, 2021). "Conversely, Vav3-deficient mice on high-fat diet were protected from obesity and metabolic syndrome due to increased levels of energy consumption per lean mass and brown adipose tissue thermogenesis." (PMID 33923452, 2021). "In vivo studies demonstrated the involvement of the Rho GEFs P-Rex2, Vav2, Vav3 and PDZ-RhoGEF in glucose tolerance and/or insulin sensitivity, with deletion of these GEFs either contributing to the development of metabolic syndrome or protecting from it." (PMID 33923452, 2021). "In vivo studies in mice have shown the Rho GEFs P-Rex2, Vav2, Vav3 and PDZ-RhoGEF to be involved in glucose tolerance and/or insulin sensitivity, with deletion of these GEFs either contributing to the development of metabolic syndrome or protecting mice from this disease." (PMID 33923452, 2021).
myocardial infarction (2 papers, 2023 to 2025). Gross necrosis of the myocardium, as a result of interruption of the blood supply to the area, as in coronary thrombosis. "Previous research has revealed a link between VAV3 and inflammation and infection, with studies showing that overexpression of VAV3 could mitigate cardiomyocyte inflammation and apoptosis in rats with myocardial infarction." (PMID 40626048, 2025).
neuronal tumor (2 papers, 2023 to 2024). Neuronal brain tumors are an uncommon group of central nervous system tumors that arise from cells with neuronal differentiation. "TAFA1, ALK, and VAV3 were some of the topmost DE genes in glioneuronal/neuronal tumors." (PMID 36865335, 2023).
osteoporosis (2 papers, 2022 to 2024). A condition of reduced bone mass, with decreased cortical thickness and a decrease in the number and size of the trabeculae of cancellous bone (but normal chemical composition), resulting in increased fracture incidence. "Combined, these mouse and human data highlight VAV3 and ADGRE5 as novel putative high‐BMD genes with additive effects, and potential therapeutic targets for osteoporosis." (PMID 35434450, 2022). "If these findings are confirmed, VAV3 and ADGRE5 might turn out to be novel therapeutic targets for the treatment of osteoporosis." (PMID 35434450, 2022).
rheumatoid arthritis (2 papers, 2021 to 2024). A chronic, systemic autoimmune disorder characterized by inflammation in the synovial membranes and articular surfaces. "Genetic evidence suggests that three members of the VAV family (VAV1, VAV2 and VAV3) of signal transduction proteins could play important roles in rheumatoid arthritis." (PMID 34205377, 2021). "Lastly, using triple Vav1–/–;Vav2–/–;Vav3–/– knockout mice, Faccio and coworkers have shown that the elimination of the three Vav family members can block the development of a neutrophil-dependent model of rheumatoid arthritis in mice." (PMID 34205377, 2021).
astrocytoma (1 paper, 2017). "Moreover, high expression of 7 of the high-malignant genes (C7ORF46, DUSP4, HS3ST3B1, ODZ1, TTL, VAV3, ZDHHC23) or low expression of 4 of the low-malignant genes (AKR1C3, ARHGEF10L, SMAD7, ST3GAL6) was associated with a lower progression free survival probability of grade III astrocytoma patients." (PMID 29152145, 2017).
atherosclerosis (1 paper, 2022). A disease characterized by the build-up of fatty material and calcium deposition in the arterial wall resulting in partial or complete occlusion of the arterial lumen. "A total of 6 genes were enriched in the lipid and atherosclerosis signaling pathway (CAMK2B, VAV3, PLCB3, NFATC3, TNFRSF10B, and BCL2L1), and these genes were regulated by tRF-60:76-Val-AAC-1-M5." (PMID 36247465, 2022).
Barrett esophagus (1 paper, 2025). Esophageal lesion lined with columnar metaplastic epithelium which is flat or villiform. "In recent years, esophageal sponge cytology combined with biomarkers, like TFF3, tissue factor pathway inhibitor 2 (TFPI2), vav guanine nucleotide exchange factor 3 (VAV3), and microRNA, have been validated to have high efficiencies in detecting Barrett's esophagus and associated adenocarcinoma." (PMID 39856802, 2025).
bladder cancer (1 paper, 2023).
buphthalmos (1 paper, 2010). "As histopathological examination of globes from mice with buphthalmos frequently demonstrated angle closure, we compared the iridocorneal angle histology of 20 Vav2/Vav3-deficient (Vav2−/−Vav3−/−) mice with wild-type mice at both 7 and 12 weeks of age." (PMID 20140222, 2010). "Eyes of Vav2/Vav3-deficient (Vav2−/−Vav3−/−) mice were noted to develop buphthalmos starting between 6 and 12 weeks of age." (PMID 20140222, 2010). "As we observed the development of buphthalmos, we assessed for elevated IOP in Vav2−/−Vav3−/−, Vav2-deficient (Vav2−/−), and Vav3-deficient (Vav3−/−) mice." (PMID 20140222, 2010). "Specifically, we show that Vav2/Vav3-deficient mice have elevated IOP, which eventually manifests as buphthalmos." (PMID 20140222, 2010).
carcinoma in situ (1 paper, 2013). "By contrast, we observed that Vav2−/−;Vav3−/− FVB mice displayed lower kinetics of tumor development, a ≈5-fold reduction in the total number of tumors developed per mouse, and 10-fold lower levels of carcinoma in situ when subjected to the two-step DMBA/TPA carcinogenic method." (PMID 23935450, 2013).
colitis (1 paper, 2013). Inflammation of the colon. "Combined methodology incorporating genetic, transcriptional and pathway data allowed identification of biologically relevant candidate genes, with Vav3 newly implicated as a colitis susceptibility gene of functional relevance." (PMID 23442222, 2013). "Phenotypic pathway analysis, text mining and time-course qPCR replication highlighted several potential cis-QTL candidate genes in colitis susceptibility, including FcgR1, Ptpn22, RORc, and Vav3." (PMID 23442222, 2013). "This approach is particularly useful for hypothesis generation, and has positionally implicated Vav3 as a biologically relevant gene candidate in colitis." (PMID 23442222, 2013).
glaucoma (1 paper, 2010). Increased pressure in the eyeball due to obstruction of the outflow of aqueous humor. "Here we demonstrate that deficiency of Vav2 and Vav3, guanine nucleotides exchange factors for Rho guanosine triphosphatases, leads to an ocular phenotype similar to human glaucoma." (PMID 20140222, 2010). "The Vav2/Vav3-deficient mouse has several characteristics which make it particularly useful as an animal glaucoma model." (PMID 20140222, 2010). "Vav2/Vav3-deficient mice, and to a lesser degree Vav2-deficient mice, show early onset of iridocorneal angle changes and elevated intraocular pressure, with subsequent selective loss of retinal ganglion cells and optic nerve head cupping, which are the hallmarks of glaucoma." (PMID 20140222, 2010). "Vav2/Vav3-deficient mice should serve not only as a useful murine model of spontaneous glaucoma, but may also provide a valuable tool in understanding of the pathogenesis of glaucoma in humans, particularly the determinants of altered aqueous outflow and subsequent elevated intraocular pressure." (PMID 20140222, 2010). "We believe that Vav2/Vav3-deficient mice will serve not only as a useful murine model of spontaneous glaucoma, but may also provide a valuable tool in understanding of the pathogenesis of glaucoma in humans, particularly the determinants of altered aqueous outflow and elevated IOP." (PMID 20140222, 2010). "The most significant advantage of this mouse glaucoma model is that the deleted genes, Vav2 and Vav3, are well-focused targets that have been studied over 20 years providing a useful starting point for further investigation of the potential molecular mechanisms underlying this phenotype." (PMID 20140222, 2010). "The elevation of IOP in Vav2/Vav3-deficient mice is accompanied by an optic neuropathy characterized by selective loss of retinal ganglion cells (RGCs) and optic nerve head (ONH) excavation and is therefore consistent with glaucoma." (PMID 20140222, 2010). "In addition, a genome-wide association study screening glaucoma susceptibility loci using single nucleotide polymorphisms analysis identified VAV2 and VAV3 as candidates for associated genes in Japanese open-angle glaucoma patients." (PMID 20140222, 2010). "While so far there are several reports of glaucoma associated candidate genes based on the single nucleotide polymorphisms (SNPs) study in the Japanese population, our data first suggest that VAV2 and VAV3 are susceptibility loci in Japanese primary open–angle glaucoma (POAG) cases." (PMID 20140222, 2010).
hepatoma (1 paper, 2021). "At present, limited studies on PIK3CD, HRAS, E2F2, BIGF1, WNT4, and VAV3 genes have been reported in hepatoma cells, indicating the need for further research." (PMID 33959508, 2021).
kidney cancer (1 paper, 2024). Primary or metastatic malignant neoplasm involving the kidney. "Our pooled analysis of 19 studies indicated that VAV3 may have tumor-suppressive properties, as it is downregulated in kidney cancers, and that higher VAV3 mRNA expression levels were associated with better survival outcomes in patients with RCC." (PMID 39200159, 2024).
left ventricular hypertrophy (1 paper, 2017). Enlargement of the LEFT VENTRICLE of the heart. "In addition, downregulation of vav guanine nucleotide exchange factor 3 (VAV3) may also indicate cardiac dysfunction in Ross broilers under heat stress, because VAV3-deficient mice exhibited left ventricular hypertrophy, systemic arterial hypertension and tachycaridia." (PMID 28407751, 2017).
lymphadenopathies (1 paper, 2022). "Consistent with our previous reports, the transplantation of p190-BCR-ABL-expressnig WT or Vav3−/− leukemic LDBM cells leads in both cases to leukemogenesis as demonstrated by the detection of lymphadenopathies, hepatosplenomegaly, and extraosseus tumors in head and neck (data not shown)." (PMID 35650206, 2022).
lymphoid leukemia (1 paper, 2022). A malignant lymphocytic neoplasm of B-cell or T-cell lineage involving primarily the bone marrow and the peripheral blood. "The reduced proliferation of Vav3-deficient lymphoid leukemia B-cell progenitors is associated with increased expression of at least Cdkn2a and Cdkn2b, genes known to be regulated by PRC." (PMID 35650206, 2022). "However, the underlying molecular mechanisms of Vav3 regulation of lymphoid leukemia B-cell progenitor proliferation remains unclear." (PMID 35650206, 2022).
memory impairment (1 paper, 2025). "Specific targets, such as NFKBIA, Cxcl12 (C‐X‐C motif chemokine ligand 12) and Vav3, along with key signalling pathways like chemokine, Wnt and NF‐kappa B, may mediate the effects of exercise on METH‐induced learning and memory impairments." (PMID 40782057, 2025).
meningioma (1 paper, 2019). A generally slow growing tumor attached to the dura mater. "Other molecules expression such as Vav3, SPARC, p-Akt, cyclin D1 and Ki-67 were found in meningiomas and correlate with meningioma invasiveness, aggressiveness and recurrence." (PMID 31123490, 2019).
osteopetrosis (1 paper, 2013). Osteopetrosis, also known as marble bone disease, is a descriptive term that refers to a group of rare, heritable disorders of the skeleton characterized by increased bone density on radiographs. "The GEF Vav3 is crucial for Rac activation and subsequent cytoskeletal rearrangement in osteoclasts as evidenced by osteopetrosis in Vav3−/− or Vav1−/−Vav3−/− mice." (PMID 23296124, 2013).
ovarian carcinoma (1 paper, 2018). A malignant neoplasm originating from the surface ovarian epithelium. "In a study on ovarian cancer, we recently demonstrated pronounced prognostic and predictive value of Vav3.1, a specific truncation variant of the parental Vav3 gene." (PMID 30083818, 2018).
papilloma (1 paper, 2013). A benign epithelial neoplasm that projects above the surrounding epithelial surface and consists of villous or arborescent outgrowths of fibrovascular stroma. "The cancer-linked phenotype of Vav2/Vav3-deficient mice is also quite different from that previously reported for Tiam1-deficient mice during both tumor initiation and papilloma/cSCC malignant progression." (PMID 23935450, 2013). "We observed that the Vav2/Vav3-dependent Tgfa, Hgf, Fgf7, and Il6 transcripts showed reduced abundance in papillomas derived from Vav2/Vav3-deficient mice when compared to the levels present in control mouse tumors." (PMID 23935450, 2013). "Expression analyses indicated that mouse papillomas and cSCCs expressed large numbers of Rho GEFs, including Vav2 and Vav3." (PMID 23935450, 2013). "This biological program may play roles in both inchoate and fully established tumors, as indicated by the similar regulation of the TPA-induced Vav2/Vav3-dependent gene signature in papillomas and cSCCs obtained from DMBA/TPA-treated mice." (PMID 23935450, 2013). "Other Vav2/Vav3-dependent (Areg, Hbegf) and -independent (Egf, Btc [ID number: 12223]) transcripts displayed similar levels in papillomas regardless of the Vav2/Vav3 expression status, further suggesting that the autocrine/paracrine defect was ameliorated in these tumors." (PMID 23935450, 2013).
rectal cancer (1 paper, 2015). A primary or metastatic malignant neoplasm that affects the rectum. "To determine the effect of VAV3 overexpression on the prognoses of two groups of colon and rectal cancer patients, we used the combined samples of data sets one and two for this analysis." (PMID 25791293, 2015). "We found that for both groups of colon and rectal cancer patients, patients with colon and rectal cancers concomitant VAV3 overexpression had a significantly lower 10-year overall survival rate than those with colon and rectal cancers without VAV3 overexpression (P = 0.002 and 0.021, respectively)." (PMID 25791293, 2015).
thyroid cancer (1 paper, 2017). "VAV3 expression in thyroid cancer cells is also known to be RET/PTC and RAS mutation-specific because VAV3 is involved in PI3K signalling and the subsequent AKT activation." (PMID 28703219, 2017).
thyroid tumor (1 paper, 2012). A benign or malignant neoplasm affecting the thyroid gland. "VAV3 is also expressed in the thyroid and is down-regulated in a subset of thyroid tumors." (PMID 22493691, 2012).
triple-negative breast carcinoma (1 paper, 2026). An invasive breast carcinoma which is negative for expression of estrogen receptor (ER), progesterone receptor (PR), and human epidermal growth factor receptor 2 (HER2). "As a guanine nucleotide exchange factor, VAV3 relates to the pathophysiology of triple-negative breast cancer (TNBC) by promoting cytoskeletal remodeling and metastatic potential through activation of Rho family GTPases." (PMID 41516402, 2026).
Yersinia infection (1 paper, 2024). "From the KEGG map of Yersinia infection, it is evident that significant methylation changes in VAV3, TBK1, and NFATC1 subsequently influence the downstream interferon response and immune cell response." (PMID 38886689, 2024).